TNF (tumor necrosis factor)
Diseases named in the same sentence as TNF in open-access papers (continued):
Sharing a sentence is not in itself a finding about the gene and the disease.
ulcer (continued). "All these events initiate an inflammatory phase of ulcer development with recruitment and metabolic activation of neutrophils and macrophages, releasing pro-inflammatory cytokines (TNF-α and IL-1β) and generating free radicals." (PMID 24416280, 2014). "Cutaneous leishmaniasis (CL) due to L.braziliensis infection is characterized by a strong inflammatory response with high levels of TNF and ulcer development." (PMID 25393535, 2014). "The inhibition of MPO (a marker of neutrophils infiltration) and TNF-α levels by RGal treatment suggests a reduction of neutrophils migration at the ulcer site and consequently promotes an improvement of the gastric inflammatory process induced by acetic acid." (PMID 24416280, 2014). "Sesamol significantly decreased gastric ulceration and hemorrhage and inhibited mucosal TNF-α, IL-1β, and IL-6 production and NF-κB activity in WIR-treated rats." (PMID 23984371, 2013). "Conversely, immunoneutralization of HMGB1 or inhibiting the release of HMGB1 promotes ulcer healing while reducing TNFα expression and MPO activity." (PMID 24244627, 2013). "Of the 24 subjects with active ulcers, TNF-α was detectable in 18 and IL-1β was detectable in 14 participants." (PMID 23922670, 2013). "Ulcer index was calculated based upon the product of length and width (mm2/rat) of ulcers while, TNF-α, IL-1β and TGF-α were estimated in the gastric mucosal homogenate from the intact/ulcer region." (PMID 24192345, 2013). "Development of the classical ulcer coincides with a great increase in TNF and IFN-γ and low levels of IL-10." (PMID 23060880, 2012). "TNF-α is a potent stimulator of neutrophil infiltration and plays a crucial role in the progression of ulcer injury via production of the injurious ROS." (PMID 27990201, 2009). "Morerecently, a study investigating functional gene polymorphisms in people with RAS showed a marked increase in the IL-1β and TNF heterozygousgenotypes in ulcer sufferers." (PMID 19259334, 2008). "Our findings corroborate earlier research indicating that OMP, used as a reference drug, significantly diminished the levels of HMGB1, NF-κB p65, and NLRP3 in comparison to the ulcer group and substantially reduced the levels of IL-1β, IL-6, and TNF-α in gastric mucosa." (PMID 40563542, 2025). "TNF-α promotes neutrophil infiltration into the gastric mucosa, triggering an inflammatory response that can impede microcirculation at the ulcer periphery, cell proliferation, and vascular regeneration, hence prolonging ulcer healing." (PMID 40563542, 2025). "Unlike exogenous growth factor interventions, harnessing endogenous NO for healing aligns more closely with physiological processes, also it can effectively remove pro‐inflammatory factors such as TNF‐α and IL‐6, illuminating its significant potential in advancing ulcer healing therapies." (PMID 40548949, 2025). "TNF-alpha blockade top-up was efficient regarding weight gain, ulcers, and inflammatory syndrome." (PMID 39156024, 2024). "Furthermore, Pioglitazone demonstrated a gastroprotective effect against ethanol induced ulcer via inhibition of nitric oxide synthase activity and decreasing the level of IL-1β and TNF-α." (PMID 38441571, 2024). "In the gastric tissue and serum samples of saline-treated ulcer group, levels of the pro-inflammatory cytokines TNF-α and IL-1β were both elevated as compared to control group (p < 0.001), while the anti-inflammatory IL-10 level was depressed (p < 0.001–0.001)." (PMID 38227096, 2024). "TNF‐α and IL‐6 levels dropped in the treated groups as compared to the ulcer group; these changes were significant for TNF‐α in the Jangale (56.9%) and eucalyptus (52.39%) groups, and for IL‐6 in the Chand Giah (30.37), Annaab (70.22), and eucalyptus (79.2%) groups." (PMID 39723096, 2024). "Increased TNF-α is associated with elevated MMP expression, a hallmark of chronic wounds, driving ECM degradation; this inhibition in TNF-α may play a part in reducing the chronicity of the ulcers." (PMID 36979379, 2023).
ulcer (continued). "However, this is the first time that the inhibitory effects of FA treatment on gastric TNF-α and IL-6 levels have been demonstrated in an indomethacin-induced ulcer." (PMID 36836745, 2023). "The concentration of TNF-α in wound fluid of unhealed ulcer is higher than that of healed ulcer." (PMID 38076422, 2023). "Furthermore, rats with acetic acid-induced gastric ulcer had lower serum TNF-α levels, and higher IL-10 levels compared to the untreated ulcer control." (PMID 35631425, 2022). "In addition, the increasing epithelial thickness and improved ulcer healing can be attributed to the anti-inflammatory effect of α-M, which suppresses the production of TNF-α and inhibits cytokine synthesis." (PMID 36015335, 2022). "TNF-α stimulates neutrophil infiltration, promotes IL-1β production and epithelial cell apoptosis, inhibits the recovery of microcirculation around ulcer, and delays ulcer healing." (PMID 34159200, 2021). "Another investigation using a mouse model of ethanol-induced ulcer found that pretreatment with oral ORV reduced ulcer scores and ulcer index, as determined from the increased gastric pH and the decreased expression levels of IL-6, TNF-α, NF-ĸB, and COX-2, with unaltered COX-1 expression levels." (PMID 34299485, 2021). "Results of IL-1β and TNFα cytokines analysis showed that administration of both doses of Hypericum perforatum decreased the level of IL-1β and increased the level of TNFα cytokines in comparison to the ulcer control group (10% Tween 20)." (PMID 33102861, 2020). "In addition, ulcers in diabetic patients show a complete derangement of inflammation mediators: interleukin (IL)-1β, IL-6, tumor necrosis factor-α (TNF-α)." (PMID 33227909, 2020). "We evaluated serum levels of TNF-α 1 hour after ulcer induction." (PMID 31516854, 2019). "For example in MRSA-infected mice ulcers, treatment with Epinecidin-1 decreased serum levels of the proinflammatory cytokines TNF-α, IL-6, and MCP-1, and regulated the recruitment of monocytes and clearance of lymphocytes around the wounded region during healing." (PMID 31138331, 2019). "MSE was reported to reverse the increase of TNF-α and IL-1β in GU induced by AA in normal rats and promoted ulcer healing by its various effects on gastric mucosal defensive factors including enhanced cell proliferation and antioxidants and reducing free radicals levels." (PMID 24192345, 2013). "Therefore, deactivating TNF-α in the ulcer area enhances ulcer healing." (PMID 37577271, 2023). "However, only PS reduced NO, TNF-α, and IL-6 levels, which were upregulated in this ulcer model." (PMID 36712695, 2022). "TNF-α plays a major role in indomethacin-induced gastric mucosal injury, as it reduces blood flow to the gastric mucosa and increases the gene expression of gastrin and vascular endothelial growth factor in the gastric mucosa, and thus hinders the ulcer healing process." (PMID 33530540, 2021). "In addition to alleviation of blood flow around the ulcer area and intensifying inflammation, TNF-α activates NF-κB that incorporates in the signal transduction inflammatory pathway activating other inflammatory genes, including COX-2 and iNOS, and amplifying ulceration." (PMID 32549800, 2020). "Compared with the oral ulcer + saline group, the nicotine-treated group showed greater epithelial thickness, lower fibrosis, lower MDA and TNF-α levels, and higher VEGF-A and EGFR levels at the study endpoint." (PMID 42195153, 2026). "TNF-α and IL-6 are key mediators of gastric inflammation, with TNF-α initiating acute inflammatory responses and delaying ulcer healing by inhibiting angiogenesis and cell proliferation." (PMID 39859072, 2025). "In the present study, a progressive increase in the levels of IL-6, TNF-α, and CRP was observed across the control, pre-ulcer, and ulcer groups, indicating that inflammation plays a critical role in the early pathogenesis of DFUs." (PMID 40364880, 2025).
ulcer (continued). "BXD further reduces gastric inflammation by lowering levels of pro-inflammatory cytokines, including interleukin (IL)−2, IL-8, and tumor necrosis factor-alpha (TNF-α), in preclinical ulcer models." (PMID 40102869, 2025). "Data were collected on demographics, ulcer severity (Wagner Grade), glycemic status (HbA1c), biochemical markers (C-reactive protein [CRP], interleukin-6 [IL-6], tumor necrosis factor-alpha [TNF-α], and serum albumin), and clinical outcomes." (PMID 40821188, 2025). "Our study revealed a significant increase in IL-6, TNF-α, and CRP levels in ulcer patients compared to the pre-ulcer and control groups." (PMID 40364880, 2025). "A direct comparison between the ulcer + OMP and ulcer + OMP-NS groups revealed that the OMP-NS formulation significantly decreased levels of HMGB1, NLRP3, NF-κB, TLR-2, MyD88, IL-1β, IL-6, and TNF-α." (PMID 40563542, 2025). "The results indicated a strong positive correlation between inflammatory biomarkers (IL-6, TNF-α, CRP) and HbA1c and ulcer severity, suggesting that increased systemic inflammation is associated with poor glycemic control and worsening ulcer conditions." (PMID 40364880, 2025). "A similar trend was observed for TNF-α (ulcer: 12.1 ± 3.0 pg/mL, pre-ulcer: 6.9 ± 1.5 pg/mL, control: 3.5 ± 0.7 pg/mL) and CRP (ulcer: 7.8 ± 1.6 mg/L, pre-ulcer: 3.4 ± 0.7 mg/L, control: 1.2 ± 0.3 mg/L)." (PMID 40364880, 2025). "In a rat DFU model, H‐ADSCs‐Exo administration reduced ulcer size, increased angiogenesis (VEGF/CD31 expression), and decreased inflammatory markers (TNF‐α, IL‐6)." (PMID 40584821, 2025). "In CL, ulcer development results from the combined presence of Th1 cytokines (such as IFN-γ and TNF), IL-1β, and cytotoxic activity from CD8 + T cells." (PMID 40982482, 2025). "Serum levels of IL-6, TNF-α, and CRP showed a progressive increase from the control group to the ulcer group, with statistically significant differences (p < 0.001)." (PMID 40364880, 2025). "DFU induces marked upregulation of inflammatory markers such as TNF-α, IL-6 and CRP, which correlate with ulcer severity." (PMID 39508881, 2025). "Ulcer group showed significant increases in MDA (64%) and TNF‐α and IL‐6 levels (98.5% and 111.6%), and decreases in ferric reducing antioxidant power and 2,2‐diphenyl‐1 picrylhydrazyl (FRAP, DPPH, and thiol levels [26%, 14.39%, and 26%]) compared to controls." (PMID 39723096, 2024). "In this study, we proposed that the ability of Cls to block ROS, IL-1β, IL-6, TNF-α, NF-κB, and caspase-3 as well as increase pErk-1, NO, PECAM-1, and PPAR-γ levels partly explains why it protects the stomach against ethanol-induced ulcer." (PMID 38884677, 2024). "Similar to omeprazole, NPW treatment significantly reduced gastric and serum tumor necrosis factor-alpha and interleukin-1 beta levels and depressed the upregulation of nuclear factor kappa B (NF-κB) and COX-2 expressions due to ulcer." (PMID 38227096, 2024). "In addition, γKetoC-treated mice showed decreased epithelial cell disruption (focal erosion and ulcers) and inflammatory cell infiltration in the colon tissue and increased number of crypts, and γKetoC administration tended to decrease concentrations of TNF-α, IL-6, and IL-12p40 in serum." (PMID 38745644, 2024). "Therefore, reducing levels of TNF-α, IL-1β, and IL-6 may promote ulcer healing." (PMID 38398633, 2024). "The wound healing process was assessed through ulcer size, traumatic ulcer healing score (UHS), collagen-1 expression (COL-1), growth factors (EGF, VEGF), pro-inflammatory markers (TNF-α), wound healing score (WHS)." (PMID 38140075, 2023). "More so than in the pre-treated animals, the EGb 761-treated groups showed improved score, levels, and expressions of the ulcer index, MDA, GSH, NO, IL-6, TNF-α, IL-1β, COX-2, and PCNA." (PMID 36080365, 2022). "In this study, pre-treatment with ZJP (1, 2, and 4 g/kg) led to a dose-dependent decrease in the contents of TNF-α, IL-6 and MPO compared with the ulcer model group." (PMID 35938492, 2022).
ulcer (continued). "Increased oxidative stress provokes the release of pro-inflammatory mediators such as interleukin-8 (IL-8), TNF-α, COX-2 upregulation, and NF-ƙB activation that plays role in inflammatory cascade further aggaravating ulcer." (PMID 36467058, 2022). "High (H-PPT) and medium (M-PPT) doses of PPT (20.0 and 10.0 mg/mg/day) significantly reduced the ulcer area and the ET-1, IL-6, EGF, SOD, MDA and TNF-α levels in serum were regulated by PPT in a dose-dependent manner." (PMID 36292949, 2022). "EFAM significantly decreased tumor necrosis factor-alpha (TNF-α) and interleukin-2 (IL-2) by 36.4% and 50.8%, respectively, in the ulcer tissues while, CEAM and BFAM exhibited lower activity at the same dose." (PMID 35161436, 2022). "While pretreatment of DTN at (30 mg/Kg) dose decreases the expression of p-NF-ĸB, TNF-α and COX2 compared to the ulcer group." (PMID 35906691, 2022). "Both BD and RAS ulcers are also positive for CD4 and CD8T cells as well as Th-1 cytokines such as IL-12, IFN-γ and TNF-α." (PMID 35003055, 2021). "Therefore, it may be perceived that reduction in the TNF-α level might facilitate ulcer healing." (PMID 34608395, 2021). "Treatment with NADA and AM630 protected gastric tissues against ulcers as demonstrated by a decrease in the contents of MDA, TNF-α, MPO, and IL-1β along with an increase in the content of PON-1 activity and GSH in the stomach tissues." (PMID 35083004, 2021). "Ulcer index, expression of gastric COX-2 gene, TNF-α, MDA, and GSH content in the stomach were measured." (PMID 33233494, 2020). "Pretreatment with genistein significantly improved ulcer indexes and increased the level of NO, PGE2 and SOD activity and significantly decreased MDA, levels of TNF-α and MPO activity, and expression of MMP-9 was negatively regulated." (PMID 33233494, 2020). "PGE2 can not only inhibit the secretion of gastric acid and stimulate tissue repair process to promote ulcer healing, but also stabilize mast cell membrane and inhibit the release of cytotoxic substances, such as PAF, TNF, and lysosomal enzyme." (PMID 30719066, 2019). "TNF-α, IL-6 and MIP-1 expression in magnet-implanted ulcers was elevated on the day after forming the ulcer (day 0) as a control (P < 0.01)." (PMID 28687753, 2017). "In contrast, administration of anti-HMGB1 antibody promoted ulcer healing and reduced MPO activity and TNFα expression." (PMID 24244627, 2013). "Recently, we reported the healing effects of ethanolic extract of dried fruit pulp of MS (MSE) on acetic acid induced gastric ulcer in normal (NR) rat and found the role of cytokines, TNF-α, IL-1β and growth factor, TGF-α in healing ulcer." (PMID 24192345, 2013). "High amounts of IFN-γ and TNF are observed in both, Leishmania antigen-stimulated PBMC cultures, and in the ulcer of CL patients." (PMID 23060880, 2012). "TNBS administration led to ulcers in the rectum, increased rectal MPO activity, and up-regulated TNF-α levels." (PMID 21853095, 2011). "In addition, sodium butyrate significantly inhibited the mRNA levels of inflammatory factors such as tumor necrosis factor-α (TNF-α), interleukin-1β (IL-1β), interleukin-6 (IL-6), and interleukin-18 (IL-18) in the ulcer tissue." (PMID 40818135, 2025). "In ethanol-induced gastric ulcer rats, DDP exerted dose-dependent protection: low doses (100 mg/kg/d) reduced ulcer index, increased SOD/GSH-Px (1.5–1.8-fold), decreased MDA (30–35%), and elevated PGE2; high doses (400 mg/kg/d) further inhibited serum TNF-α/IL-6 (25–40%) and improved histopathology." (PMID 41008230, 2025). "Considering the broad role of inflammatory cytokines in the regulation of the WH process, we evaluated the expression of COX2 and pro-inflammatory cytokines, namely IL1β, IL6, TGFβ, and TNFα, that are important for cell proliferation and the synthesis of the ECM, both in normal-HDFs and ulcer-HDFs." (PMID 38671778, 2024).
ulcer (continued). "The biomarkers selected for the panel include tumor necrosis factor–α (TNF-α), interleukin-6 (IL-6), and IL-8, which are elevated in wound fluids obtained from nonhealing ulcers as compared to healing ulcers." (PMID 34020961, 2021). "Activated fibroblasts in the ulcer bed display neutrophil-chemoattractant properties that are IL-1R, but not TNF, dependent." (PMID 34675383, 2021). "The extract significantly reduced the elevated levels of IKκB, NF-κB, TNF-α, IL-6, iNOS, and lipid peroxidation; increased the reduced level of glutathione peroxidase (GPx) activity; and reduced glutathione (GSH) in the indomethacin-induced ulcer model." (PMID 33530540, 2021). "IL-6 and TNF-α proinflammatory factors are amplified in chronic non-healing ulcers, postponing the healing process." (PMID 31137844, 2019). "However, AMHAE pretreatment displayed significant increases of IL-4 (6.92-fold) and HSP-70 (4.57-fold) levels and a decline of NF-κB p65 (2.62-fold), TNF-α (2.66-fold), and MCP-1 (6.63-fold) levels compared to the ethanol-induced ulcer control group." (PMID 28587230, 2017). "The frequency of cytokine detection in sickle cell disease patients without ulcers was lower in comparison to the ulcer group, which showed 12 of 31 presenting with detectable concentrations of TNF-α and 10 with IL-1β." (PMID 23922670, 2013). "Plasma concentrations of the proinflammatory cytokine IL1-β (pg/mL) (ssu vs. ssn median(IQR): 0.34 (1.28) vs. 0 (0.08); p = 0.0178), but not TNF-α (pg/mL) (1.99 (4.3) vs. 0.97 (3.38) was significantly greater in subjects with ulcers." (PMID 23922670, 2013). "Various cytokines may contribute to the pathogenesis of ulcers, as elevated IL-2, IFN-γ, and TNF-α, while lower concentrations of IL-10 were reported in lesions of RAS patients." (PMID 23258985, 2012). "However, despite the use of colchicine and azathioprine, our patient continued to develop recurrent non-healing ulcers, which eventually responded to anti-TNF-α." (PMID 40585706, 2025). "In such cases, the absence of a positive correlation between IL-10 not only with TNF and IFN-γ, but also with other pro-inflammatory cytokines at the lesion site suggests an impaired participation of IL-10 in the control of the inflammatory reaction resulting in tissue injury and ulcer development." (PMID 38535542, 2024). "Finally, gene ontology (GO) enrichment analysis unveiled cellular response to TNF as top biological function activated in healing ulcers and myeloid leukocyte migration in non-healing ulcers." (PMID 35013299, 2022). "Moreover, KFX (5,10 mL/kg) increased the prostaglandin E2 (52%) and cyclooxygenase-1 (30%) levels, and improved malondialdehyde (54%), superoxide dismutase (58%), catalase (39%), and nitric oxide (11%) and TNF-α (9%), IL-6 (11%), MMP-9 (54%) and MMP-2 (53%) of ulcer tissue." (PMID 31696757, 2019). "The ulcer cure rate at 1 year was 13.6% (3 of 22 patients) in the group with CS without TNF-i." (PMID 31228955, 2019). "In TLR4 KO and RAGE KO mice, exogenous HMGB1 did not affect ulcer healing and TNFα expression." (PMID 24244627, 2013). "However, an increased presence of TNF-α in the mouth of BD patients without any ulcers could lead to an influx of neutrophils which as we have previously proposed can lead to mucosal instability following an exacerbated inflammatory cycle." (PMID 35003055, 2021). "In parallel, excessive inflammation mediated by IL-6 and TNF-α remains a well-known barrier to DFU closure; elevated levels of these cytokines in non-healing ulcers lead to continual macrophage M1 polarization and inhibited keratinocyte migration." (PMID 40728954, 2025). "Increased expression of inflammatory mediators such as interleukin (IL)-8, IL-1, IL-6, and tumor necrosis factor (TNF)-α sustains a persistent pro-inflammatory environment, preventing normal tissue regeneration and resulting in a chronic nonhealing ulcer." (PMID 41463007, 2025).